BTRC (beta-transducin repeat containing E3 ubiquitin protein ligase)
Description:
Substrate recognition component of a SCF (SKP1-CUL1-F-box protein) E3 ubiquitin-protein ligase complex which mediates the ubiquitination and subsequent proteasomal degradation of target proteins. Recognizes and binds to phosphorylated target proteins. SCF(BTRC) mediates the ubiquitination of CTNNB1 and participates in Wnt signaling. SCF(BTRC) mediates the ubiquitination of phosphorylated NFKB1, ATF4, CDC25A, DLG1, FBXO5, PER1, SMAD3, SMAD4, SNAI1 and probably NFKB2. SCF(BTRC) mediates the ubiquitination of NFKBIA, NFKBIB and NFKBIE; the degradation frees the associated NFKB1 to translocate into the nucleus and to activate transcription. Ubiquitination of NFKBIA occurs at 'Lys-21' and 'Lys-22'. The SCF(FBXW11) complex also regulates NF-kappa-B by mediating ubiquitination of phosphorylated NFKB1: specifically ubiquitinates the p105 form of NFKB1, leading to its degradation. SCF(BTRC) mediates the ubiquitination of CEP68; this is required for centriole separation during mitosis. SCF(BTRC) mediates the ubiquitination and subsequent degradation of nuclear NFE2L1 (By similarity). Has an essential role in the control of the clock-dependent transcription via degradation of phosphorylated PER1 and PER2. May be involved in ubiquitination and subsequent proteasomal degradation through a DBB1-CUL4 E3 ubiquitin-protein ligase. Required for activation of NFKB-mediated transcription by IL1B, MAP3K14, MAP3K1, IKBKB and TNF. SCF(BTRC) acts as a negative regulator of smoothened signaling by mediating ubiquitination of GLI2 and GLI3 in absence of smoothened, promoting their processing into transcription repressors. Mediates ubiquitination of REST, thereby leading to its proteasomal degradation. SCF(BTRC) mediates the ubiquitination and subsequent proteasomal degradation of KLF4; thereby negatively regulating cell pluripotency maintenance and embryogenesis (By similarity). SCF(BTRC) acts as a regulator of mTORC1 signaling pathway by catalyzing ubiquitination and subsequent proteasomal degradation of phosphorylated DEPTOR, TFE3 and MITF. SCF(BTRC) directs 'Lys-48'-linked ubiquitination of UBR2 in the T-cell receptor signaling pathway.
Synonyms: BTRCP; FBW1A; FBXW1A; betaTrCP; Fwd1; beta-TrCP1; bTrCP1; BETA-TRCP; FBXW1
Tractability: Small molecule: a structure with a bound ligand is known. Antibody: the Human Protein Atlas places it where antibodies can reach. PROTAC: UniProt records ubiquitination sites on it; ubiquitination databases record sites on it.
Gene: Protein-coding gene on chromosome 10 (101,354,033 to 101,557,321, forward strand). Ensembl gene ENSG00000166167.
Subcellular location: Cytoplasm; Nucleus
Subcellular location (Human Protein Atlas): Nucleoplasm; Cytosol; Plasma membrane
Pathways (Reactome):
Immune System: Activation of NF-kappaB in B cells; Antigen processing: Ubiquitination & Proteasome degradation; CLEC7A (Dectin-1) signaling; Dectin-1 mediated noncanonical NF-kB signaling; Downstream TCR signaling; FCERI mediated NF-kB activation; GSK3B-mediated proteasomal degradation of PD-L1(CD274); Interleukin-1 signaling; MAP3K8 (TPL2)-dependent MAPK1/3 activation; NIK-->noncanonical NF-kB signaling; Prolactin receptor signaling
Signal Transduction: Deactivation of the beta-catenin transactivating complex; Degradation of GLI1 by the proteasome; Degradation of GLI2 by the proteasome; Degradation of beta-catenin by the destruction complex; GLI3 is processed to GLI3R by the proteasome
Cell Cycle: Regulation of PLK1 Activity at G2/M Transition; SCF-beta-TrCP mediated degradation of Emi1; Ubiquitin-Mediated Degradation of Phosphorylated Cdc25A
Cellular responses to stimuli: GSK3B and BTRC:CUL1-mediated-degradation of NFE2L2
Circadian clock: Degradation of CRY and PER proteins
Disease: Vpu mediated degradation of CD4
Metabolism of proteins: Neddylation
Gene Ontology:
Molecular function: beta-catenin binding; protein binding; ubiquitin ligase activator activity; ubiquitin-like ligase-substrate adaptor activity; protein dimerization activity; protein phosphorylated amino acid binding; ubiquitin protein ligase activity
Biological process: negative regulation of smoothened signaling pathway; negative regulation of T cell receptor signaling pathway; non-canonical NF-kappaB signal transduction; proteasome-mediated ubiquitin-dependent protein catabolic process; protein K48-linked ubiquitination; protein polyubiquitination; protein processing; protein ubiquitination; regulation of circadian rhythm; SCF-dependent proteasomal ubiquitin-dependent protein catabolic process; ubiquitin-dependent protein catabolic process; negative regulation of transcription by RNA polymerase II; positive regulation of circadian rhythm; positive regulation of DNA-templated transcription; protein dephosphorylation; regulation of canonical Wnt signaling pathway; regulation of cell cycle process; signal transduction
Cellular component: SCF ubiquitin ligase complex; cytoplasm; cytosol; nucleoplasm; nucleus
Genetic constraint (gnomAD): Loss-of-function variants: 31 observed, 65.02 expected, observed/expected ratio (o/e) 0.48, 90% interval 0.36 to 0.64. The upper end of that interval is the gene's LOEUF score, 0.64, which puts it in group 2 of 6, group 1 being the genes least tolerant of losing a copy. Missense variants: 524 observed, 669.77 expected, observed/expected ratio (o/e) 0.78, 90% interval 0.73 to 0.84. Synonymous variants: 225 observed, 244.02 expected, observed/expected ratio (o/e) 0.92, 90% interval 0.83 to 1.03.
Homologues: Orthologues: chimpanzee BTRC (99% identical), dog BTRC (99% identical), pig BTRC (99% identical), mouse Btrc (99% identical), rat Btrc (99% identical), guinea pig BTRC (94% identical), rabbit BTRC (93% identical), macaque BTRC (92% identical), tropical clawed frog btrc (92% identical), Drosophila melanogaster slmb (65% identical), Caenorhabditis elegans sel-10 (17% identical). Paralogues in human: FBXW11 (78% identical), FBXW7 (21% identical), TRAF7 (16% identical), EFCAB8 (15% identical), WDR49 (15% identical), WDR86 (14% identical), FBXW9 (13% identical), WDR64 (13% identical), FBXW8 (11% identical), PAAF1 (10% identical), FBXW12 (8% identical), WDR54 (8% identical), and 2 more.
Diseases named in the same sentence as BTRC in open-access papers:
BTRC is named in the same sentence as 86 diseases in open-access papers, as found by Europe PMC text mining. Sharing a sentence is not in itself a finding about the gene and the disease. The quoted sentences say what the papers report.
breast cancer (41 papers, 2010 to 2025). A primary or metastatic malignant neoplasm involving the breast. "Consistently, we observed that combinatorial gene expression of WBP2, BTRC, and inverted IκBα associates with poorer prognosis in clinical breast cancer patients." (PMID 34197030, 2022). "Therefore, our findings concur with the notion that WBP2 is positively associated with BTRC in breast cancer, especially in TNBC." (PMID 34197030, 2022). "Therefore, the WBP2/BTRC/IκBα signaling axis was associated with poorer survival outcomes in clinical breast cancer, especially in basal breast cancer, in congruence with the findings presented in this study." (PMID 34197030, 2022). "The expression of human BTRC (beta-transducing repeat-containing protein), which contains one F-box and seven WD-repeats, targeted to epithelial cells under tissue specific promoter in BTRC deficient (−/−) female mice, promoted the development of mammary tumors." (PMID 23514407, 2013). "Because BTRC can either act as a tumor suppressor or promoter in various cancers, we validated its role in breast cancer by performing Kaplan–Meier survival analysis based on its protein expression." (PMID 34197030, 2022). "Given that WBP2 promotes BTRC expression, we investigated their coexpression in a breast cancer cell line panel." (PMID 34197030, 2022). "Together, all these findings provided evidence that WBP2 promotes breast cancer by downregulating IκBα through driving BTRC expression." (PMID 34197030, 2022). "In fact, it has been observed that DNMT1 and E2F3 are candidate targets of miR-152 in HCC, endometrial and breast cancer; BTRC has been shown to ubiquitinate phosphorylated NFKBIA, targeting it for degradation and thus activating NF-κB." (PMID 25330074, 2014). "Finally, the mammalian ortholog of Slmb, BTRC, has been shown to ubiquitinate ULK1 in breast cancer cells, leading to mitophagy deficiency and cancer cell metastasis." (PMID 40240351, 2025). "Our results showed that BTRC acts as an oncogene in breast cancer." (PMID 34197030, 2022). "Together, these in vitro findings led us to the hypothesis that elevated WBP2 and BTRC expression, coupled with reduced IκBα expression, predicts poorer prognosis for clinical breast cancer." (PMID 34197030, 2022). "Strong linkage between these well-studied breast-cancer-related genes and other identified genes makes the identified, but under-studied, genes more reasonable targets for further experimental investigation, such as BTRC and PLK1." (PMID 34290286, 2021). "Additionally, a survey of public microarray data repositories for survival among 5667 breast cancer patients in KM plotter database demonstrated that elevated WBP2/BTRC/IκBα gene signature is significantly correlated to distant metastasis‐free survival (DMFS) with a hazard ratio (HR) of 1.37." (PMID 34197030, 2022). "For instance, in breast cancer, GPT2-enriched exosomes activate BTRC to promote metastasis." (PMID 41323791, 2025). "In addition, the other three host genes (GNA12, BTRC, and MS4A7) correlated to lncRNA expression have been demonstrated to be associated with cancer progression, and specifically, the enhancement of BTRC expression could facilitate M2 macrophage polarization in breast cancer." (PMID 39126025, 2024). "With consideration of the tumor‐promoting role of BTRC, and the positive regulatory role of WBP2 on BTRC, we questioned whether WBP2 mediates breast cancer migration and invasion via BTRC." (PMID 34197030, 2022).
lung cancer (19 papers, 2015 to 2025). A malignant neoplasm involving the lung. "The findings of the inhibitory effects of BTRC on cell growth and tumor formation, as well as down-regulation of BTRC expression in lung cancer suggest that BTRC gene may function as a tumor suppressor to prevent the development of cancer." (PMID 26497204, 2015). "BTRC was also demonstrated to be an important factor in the process of EMT because of βTrCP-mediated ubiquitination of Snail in lung cancer, which inhibition of βTrCP resulted in the upregulation of Snail could induce EMT." (PMID 26497204, 2015).
colorectal cancer (15 papers, 2014 to 2024). A primary or metastatic malignant neoplasm that affects the colon or rectum. "High levels of BTRC mRNA and β-TrCP1 have been found in tumor samples from patients with colorectal cancer compared to normal tissues." (PMID 37686524, 2023). "β-TrCP (BTRC, Fbxw11) is also mutated in several cancers, including breast and colorectal cancer and melanoma, potentially stabilising its oncogenic substrate β-catenin." (PMID 31560077, 2020). "Induced BTRC and CRDBP expression was associated with the activation of both β-catenin and NF-κB in colorectal cancer, implying that integration of these pathways by βTrCP and CRD-BP might contribute to a reduction in tumor cell apoptosis and promotion of tumor metastasis." (PMID 27713747, 2016).
hepatocellular carcinoma (13 papers, 2016 to 2025). A malignant tumor that arises from hepatocytes. "A 9 bp insertion or deletion (9N ins/del) polymorphism (rs16405) in the 3′-UTR of the BTRC gene has been negatively associated with hepatocellular carcinoma (HCC) risk in a Chinese population." (PMID 37686524, 2023). "In summary, CDK1, CCND1, RAF1, CDKN1B and BTRC were defined as top 5 hub target-genes, and the patients with hepatocellular cancer with high expression of CDK1 showed poor prognosis." (PMID 35836300, 2022). "CHEK1, CDC25A, and CCNE1, together with CCND1, CCND3, CDK4, CDK6, BTRC, E2F3, and FOXK1, were previously identified as the targets of miR‐497∼195 cluster in hepatocellular carcinoma." (PMID 40548926, 2025).
glioma (11 papers, 2015 to 2024). A benign or malignant brain and spinal cord tumor that arises from glial cells (astrocytes, oligodendrocytes, ependymal cells). "Nevertheless, further investigations are still needed to unravel the precise mechanism underlying the regulation of miR-193a-3p/BTRC axis in glioma." (PMID 33628829, 2021). "Collectively, these results demonstrated that BTRC expression was decreased in glioma tissues, and its expression levels were associated with a favorable prognosis of patients with glioma." (PMID 33628829, 2021). "USP7, UBE2G2, and BTRC were associated with better prognosis of glioma(HR<1, P<0.001)." (PMID 35774799, 2022). "The results suggest that miR-193a-3p promotes malignant phenotypes of glioma cells in a BTRC-dependent manner." (PMID 33628829, 2021). "Then, we explored the effects of miR-193a-3p on the invasion and migration of glioma cells by targeting BTRC through transwell and wound-healing assays." (PMID 33628829, 2021). "Upregulated miR-193a-3p or downregulated BTRC can significantly promote the invasion, migration, and MT of glioma cell lines." (PMID 33628829, 2021). "Survival analysis demonstrated that the expression of BTRC was significantly correlated with the prognosis of patients with glioma." (PMID 33628829, 2021). "In our study, the downregulated BTRC can obviously reverse the effects of miR-193a-3p inhibitor on the cell invasion, migration, and MT of glioma in vitro, suggesting BTRC functions as a tumor suppressor." (PMID 33628829, 2021). "This study has not only experimentally verified the role of miR-193a-3p in glioma, but suggested a network for miR-193a-3p to promote tumor progression through BTRC." (PMID 33628829, 2021). "It provided a basis for miR-193a-3p and BTRC as biomarkers and therapeutic targets for glioma prognosis." (PMID 33628829, 2021). "Starbase database was used to predict the relationship between miR-193a-3p and BTRC protein expression level in patients with glioma." (PMID 33628829, 2021). "Next, HPA database showed that the protein expression of BTRC was downregulated in glioma tumor tissues compared to normal ones." (PMID 33628829, 2021). "Our study reveals that high expression of miR-193a-3p and low level of BTRC indicated worse overall survival for patients with glioma." (PMID 33628829, 2021). "In conclusion, high expression of miR-193a-3p and low level of BTRC indicated worse overall survival for patients with glioma." (PMID 33628829, 2021). "Transwell, wound healing, and Western blot experiments were performed to investigate the effects of miR-193a-3p and beta-transducin repeat containing E3 ubiquitin protein ligase (BTRC) on the invasion, migration, and MT of glioma." (PMID 33628829, 2021). "The results from the transwell, wound healing, and Western blot analyses suggested that miR-193a-3p promoted the invasion, migration, and MT of glioma cells, which could be reversed by BTRC." (PMID 33628829, 2021). "And upregulated miR-193a-3p could promote the invasion, migration, and MT of glioma by downregulating BTRC." (PMID 33628829, 2021). "In this study, we proved that miR-193a-3p could bind to the 3′UTR of BTRC and its overexpression resulted in increased N-cadherin but decreased T-cadherin and BTRC in glioma cells." (PMID 33628829, 2021). "miR-193a-3p was upregulated in patients with glioma and could affect the invasion, migration, and MT of glioma by regulating BTRC." (PMID 33628829, 2021). "Taken together, our results demonstrate that miR-193a-3p and BTRC may serve as a promising therapeutic target for glioma." (PMID 33628829, 2021). "However, whether miR-193a-3p is involved in the invasion and migration of glioma by binding to BTRC remains poorly understood." (PMID 33628829, 2021). "In our study, we prove that miR-193a-3p was highly expressed in glioma, suppressing BTRC expression through directly targeting the 3′UTR of BTRC, suggesting the probable role of absent miR-193a-3p in the upregulation of BTRC." (PMID 33628829, 2021).
liver cancer (10 papers, 2016 to 2024). An epithelial or non-epithelial malignant neoplasm that arises from the liver. "In four cancers, mutations at the N-terminal disordered region of the protein are predicted to perturb interactions with BTRC, FBXW11 and HLA-A, whereas only two of these cancers (liver cancers) have additional mutations at the armadillo region perturbing interactions with other proteins." (PMID 27698488, 2016).
prostate carcinoma (9 papers, 2004 to 2025). A carcinoma that arises from epithelial cells of the prostate gland. "Interestingly, we detected an association between patient survival and gene expression of USP9X only, but not of HUWE1, BTRC, and FBXW7, even though all gene products are able to interact with Mcl-1, further emphasizing the role of the deubiquitinase in prostate cancer progression." (PMID 37173959, 2023).
colon carcinoma (8 papers, 2014 to 2022). "The EBV-miRNA miR-BART10-3p, which we found elevated in tumor tissue was previously found to directly targets BTRC, a gene found to be upregulated in colon cancer." (PMID 30786859, 2019).
esophageal squamous cell carcinoma (7 papers, 2020 to 2025). Esophageal squamous cell carcinoma (ESCC) is a type of esophageal carcinoma (EC) that can affect any part of the esophagus, but is usually located in the upper or middle third. "In esophageal squamous cell carcinoma, Circ_0001821 affects cell proliferation and the cell cycle by enhancing BTRC-mediated IKBA ubiquitination." (PMID 40413536, 2025). "BTRC can interact with TSPAN15 and promotes esophageal squamous cell carcinoma metastasis by activating NF-kB signaling." (PMID 36199080, 2022).
melanoma (6 papers, 2015 to 2023). A malignant, usually aggressive tumor composed of atypical, neoplastic melanocytes. "Mechanistically, DHC accelerates ubiquitination of β-catenin and up-regulates the beta-transducin repeat containing E3 ubiquitin protein ligase (BTRC) in melanoma cells." (PMID 33833997, 2021).
nasopharyngeal carcinoma (5 papers, 2015 to 2025). A carcinoma arising from the nasopharyngeal epithelium. "Down-regulated BTRC is associated with poor prognosis in patients with nasopharyngeal carcinoma (NPC)." (PMID 27888627, 2016).
pancreatic cancer (5 papers, 2013 to 2025). "In a separate genome-wide association study, common variants in the SHH, BTRC and HHIP genes have been associated with the risk of pancreatic cancer." (PMID 23826113, 2013). "miR-10a and miR-182 directly bind to the 3′-UTR of BTRC, and FBXW11 degrades their mRNAs in human aortic endothelial cells and in pancreatic cancer cells, respectively." (PMID 37686524, 2023).